AXL (AXL receptor tyrosine kinase)
Diseases named in the same sentence as AXL in open-access papers (continued):
Sharing a sentence is not in itself a finding about the gene and the disease.
liver disease (6 papers, 2020 to 2025). "The GAS6/AXL pathway was expressed in the case of underlying liver disease, and its inhibition appeared after the induction of liver regeneration, resulting in immune activation." (PMID 37108648, 2023). "Together, these studies strongly supported that alcohol-associated liver disease induced ER stress and mitochondria-associated apoptosis and increased the susceptibility of mouse liver to I/R injury, and p-AXL may be involved in the pathogenesis." (PMID 39897049, 2025). "Besides being involved in immune homeostasis, MERTK and AXL were also associated with deleterious processes in some liver diseases." (PMID 37004869, 2023). "Having observed AXL up-regulation on circulatory monocytes in relation to portal hypertension, we hypothesized an underlying mechanism involving pathologic bacterial translocation leading to the abundance of bacterial products, PAMPs, and subsequent chronic systemic inflammation." (PMID 31822557, 2020). "Here, we observed strong correlations of AXL-expressing monocytes with the shed receptor sAXL and also liver disease severity scores." (PMID 31822557, 2020). "Recently, we observed circulating AXL-expressing monocytes in patients with cirrhosis of the liver in parallel with disease progression and portal hypertension characterized by preserved phagocytosis capacity but reduced T-cell activation and inflammatory cytokines suggesting a homeostatic function." (PMID 37004869, 2023). "Refractory AXL/GAS‐6 signaling, due to chronic overactivation/stimulation in the context of underlying liver disease, appears to abolish their immediate release following induction of liver regeneration, causing overwhelming immune activation, presumably via intrahepatic immune regulation." (PMID 34951136, 2022). "Its involvement in tumorigenesis and autoimmune diseases has been extensively studied; however, in liver diseases, particularly in MASH, research on the role of AXL is limited." (PMID 38817615, 2024). "AXL levels on resident liver macrophages were similarly decreased in patients with NCPH, suggesting potential involvement of mechanisms eliciting portal hypertension." (PMID 37004869, 2023). "Similarly, AXL-expressing macrophages were reduced in non-cirrhotic portal hypertension (NCPH)." (PMID 37004869, 2023).
pulmonary fibrosis (6 papers, 2019 to 2025). Chronic progressive interstitial lung disorder characterized by the replacement of the lung tissue by connective tissue, leading to progressive dyspnea, respiratory failure, or right heart failure. "GAS6/AXL pathways were associated with fibrogenesis in CLD and idiopathic pulmonary fibrosis, respectively, and were reversed by BGB324." (PMID 31822557, 2020). "Additionally, the downregulation of AXL protein expression, reversal of EMT and reduction of pulmonary fibrosis signatures suggest on-target effect." (PMID 40696160, 2025).
renal fibrosis (6 papers, 2019 to 2024). A final common manifestation of a wide variety of chronic kidney diseases characterized by glomerulosclerosis and tubulointerstitial fibrosis. "AXL targeting reduces fibrosis development in experimental renal fibrosis and in human intestinal organoid models." (PMID 36388923, 2022). "In a previous study from our group, we found that tyrosine kinase receptor AXL is involved in the progression of renal fibrosis in a UUO murine model and that AXL inhibitor bemcentinib attenuates disease development." (PMID 34219376, 2021). "Taken together, the blockade of the AXL RTK pathway reduces renal fibrosis development in the context of UUO." (PMID 31134766, 2019). "The AXL RTK pathway is involved in the pathogenesis of renal fibrosis in UUO and represents a novel and promising target for the pharmacologic prevention of fibrosis development in CKD." (PMID 31134766, 2019). "Accordingly, AXL inhibition should have beneficial effects on the renal architecture with less renal fibrosis development." (PMID 31134766, 2019). "AXL upregulation has been shown to promote iMφs in a range of settings, including postmyocardial infarction, nonalcoholic steatohepatitis, and renal fibrosis models." (PMID 38261406, 2024). "Notably, our previous work demonstrated that bemcentinib, a selective AXL inhibitor, mitigates experimental renal fibrosis by reducing p‐EMT induction, inflammation, and downregulating genes associated with fibrosis in a unilateral ureteral obstruction (UUO) mouse model." (PMID 37813528, 2023).
brain tumor (5 papers, 2011 to 2026). "According to Vouri’s study, AXL can amplify EGFR signaling by interacting with EGFR in brain tumor cells." (PMID 38338651, 2024). "To examine the pathophysiological relevance of AXL in human malignant glioma we evaluated AXL expression in brain tumor tissue by immunohistochemistry." (PMID 23077658, 2012). "It has been reported that dominant-negative inhibition of AXL suppresses brain tumor growth and invasion and prolongs survival in a mice model of gliomagenesis." (PMID 22141136, 2011).
cutaneous melanoma (5 papers, 2016 to 2024). A primary melanoma arising from atypical melanocytes in the skin. "First, analysis of 278 cutaneous melanomas (TCGA provisional RNASeqV2 RSEM) using the CBio Portal for cancer genomics indicated that AXL was co-expressed with RUNX2 (Pearson's correlation = 0.56)." (PMID 27102439, 2016). "Three cutaneous melanoma cell lines (C013M, MeWo and NM177) were classified as transitory, as they expressed elevated levels of MITF and Melan A, and intermediate/high levels of AXL and/or NGFR." (PMID 34073253, 2021). "Interestingly, the same negative correlation has been observed on MITF and AXL expression levels interrogating cutaneous melanoma data deposited in cBioPortal database." (PMID 38472212, 2024).
Ewing sarcoma (5 papers, 2014 to 2024). A small round cell tumor that lacks morphologic, immunohistochemical, and electron microscopic evidence of neuroectodermal differentiation. "Knockdown of ETS1 or inhibition of ETS1 with a pan ETS inhibitor TK216 (currently in phase I clinical trial (NCT026570095) for Ewing sarcoma), downregulated AXL, IL6, and EFEMP1, suggesting ETS1 transcriptionally activates these genes." (PMID 38762181, 2024). "AXL inhibitors were shown to affect the viability of Ewing sarcoma cells." (PMID 36980534, 2023). "A subsequent study identified AXL as a potential therapeutic target for Ewing sarcoma." (PMID 36980534, 2023). "Here, using phospho-profiling, we find Ewing sarcoma cells treated with chemotherapeutic agents activate TAM (TYRO3, AXL, MERTK) kinases to augment Akt and ERK signaling facilitating chemoresistance." (PMID 38906855, 2024). "Several of these Ewing sarcoma tumor cell–expressed genes have been previously studied in Ewing sarcoma [AXL, WNT5A, IGF-1R, TNFRSF10B (TRIAL-R2/DR5)], and have been described as potential targets in Ewing sarcoma and/or to be involved in Ewing sarcoma tumor cell migration/metastatic potential." (PMID 37823774, 2023).
leiomyosarcoma (5 papers, 2017 to 2025). An uncommon, aggressive malignant smooth muscle neoplasm, usually occurring in post-menopausal women. "Eight models with strong AXL expression (median AXL H-score > 120) were selected, representing the more common STS subtypes of dedifferentiated liposarcoma, leiomyosarcoma, myxofibrosarcoma, and undifferentiated pleomorphic sarcoma." (PMID 35886842, 2022). "Aberrant expression of the receptor tyrosine kinase AXL has recently been reported in a variety of cancers, including the more common STS subtypes such as leiomyosarcoma and liposarcoma." (PMID 35886842, 2022).
liver cancer (5 papers, 2023 to 2025). An epithelial or non-epithelial malignant neoplasm that arises from the liver. "Cabozantinib, which is a MET inhibitor, inhibits tyrosine kinases, including vascular endothelial growth factor receptors 1, 2, and 3, MET, and AXL, which are implicated in liver cancer progression." (PMID 39519229, 2024). "While all known methods to evaluate AXL expression include tissue extraction, in some forms of hepatic neoplasm, it is possible to assess clinical outcome by evaluating plasma levels of soluble AXL (sAXL)." (PMID 37469409, 2023). "Notably, IHC staining revealed medium/high PROS1 and AXL expression in liver cancers." (PMID 38254761, 2024). "Also, in a type of liver cancer (cholangiocarcinomas), OPCML enhanced the effect of bemcentinib in AXL-expressing cell lines." (PMID 40699804, 2025).
asthma (4 papers, 2017 to 2022). "To do so, we tested the interaction between PTS and AXL methylation on the risk of childhood asthma and related phenotypes." (PMID 30029617, 2018). "We investigated the association between PTS and epigenetic changes in AXL and how this was related to childhood asthma phenotypes." (PMID 30029617, 2018). "Our results show that average methylation in AXL at birth was associated with higher risk for asthma-related phenotypes in childhood, especially wheezing." (PMID 29177020, 2017). "In conclusion, AXL DNA methylation at birth, which was strongly linked to underlying genetic variation, was also associated with higher risk for asthma-related phenotypes in early childhood." (PMID 29177020, 2017). "We investigated the association between AXL DNA methylation at birth and risk of childhood asthma symptoms at age 6 years." (PMID 29177020, 2017). "None of these SNPs were confounders to the association between AXL methylation and asthma-related symptoms or statistically significantly associated with asthma and related symptoms in childhood." (PMID 29177020, 2017). "AXL DNA methylation at birth was associated with higher risk for asthma-related symptoms in early childhood." (PMID 29177020, 2017). "Furthermore, DNA methylation of AXL at birth has been associated with an increased risk of developing asthma-related responses in childhood, with girls being more affected than boys." (PMID 35415078, 2022). "We further hypothesized that AXL methylation would be associated with later childhood asthma and related symptoms through innate immune pathways involved in the pathogenesis of asthma." (PMID 30029617, 2018). "The identification of epigenetic and genetic variation associated with childhood asthma symptoms may shed light on the etiology of this complex disease and the biological role of AXL." (PMID 29177020, 2017). "We first investigated whether average DNA methylation in AXL was associated with childhood asthma symptoms." (PMID 29177020, 2017). "Lastly, although we made every effort to control for potential confounders, we cannot exclude the possibility of residual confounding by some unknown factors associated with AXL DNA methylation levels and asthma-related phenotypes." (PMID 29177020, 2017). "This information suggests that AXL signaling may be associated with the suppression of inflammatory responses and lower risk for asthma and related phenotypes." (PMID 29177020, 2017). "Given the known associations between prenatal tobacco smoke exposure and asthma risk, as well as prenatal tobacco smoke and DNA methylation in AXL, we sought to investigate whether methylation in AXL at birth was associated with childhood asthma or asthma-related symptoms." (PMID 29177020, 2017). "Higher average AXL methylation was also associated with higher risk for childhood bronchitic symptoms, which are suggestive of chronic symptoms that may follow an illness or acute exacerbation of asthma, or chronic inflammation in the airway." (PMID 29177020, 2017). "Many of the genes inhibited or activated by AXL in this process are involved in asthma pathogenesis." (PMID 29177020, 2017). "AXL has been well characterized in the pathogenesis of numerous cancers and cardiovascular events but is rarely addressed in asthma." (PMID 29177020, 2017). "The association between asthma symptoms and the blood spot-derived DNA methylation of AXL, a childhood asthma-related gene, was more apparent in girls rather than boys at the same age." (PMID 33781317, 2021). "However, the role for AXL in asthma, including its epigenetic regulation, has not been extensively studied." (PMID 29177020, 2017).
atherosclerosis (4 papers, 2016 to 2024). A disease characterized by the build-up of fatty material and calcium deposition in the arterial wall resulting in partial or complete occlusion of the arterial lumen. "The growth arrest-specific 6 (GAS6) gene and its receptor, AXL, are pivotal in vascular hemostasis and the pathogenesis of atherosclerosis." (PMID 39845086, 2024). "Proteins related to atherosclerosis/cardiovascular risk (e.g., SELE/E-selectin, IGFBP7, CHIT1/ chitotriosidase-1, AXL) also significantly decreased after treatment." (PMID 32849633, 2020). "AXL, a member of the TAM (Tyro3, Axl, MerTK) family of receptors, plays important roles in cell survival, clearance of dead cells (efferocytosis), and suppression of inflammation, which are processes that critically influence atherosclerosis progression." (PMID 27958361, 2016).
cervical carcinoma (4 papers, 2014 to 2021). A carcinoma arising from either the exocervical squamous epithelium or the endocervical glandular epithelium. "In a recent report, authors showed that AXL expression was higher in HPV type 16E6 (HPV16E6)-overexpressing HeLa cells than in the controls and the expression of AXL was correlated with clinical stage of cervical cancer and HPV16/18 infection." (PMID 34563169, 2021). "In colorectal and cervical cancer cell lines, methylation of certain transcription factor binding sites in the AXL promoter lead to decreased expression of AXL." (PMID 32148495, 2020). "MZF1 was demonstrated to bind to the AXL promoter and induced invasion and metastasis in colorectal and cervical cancer cells, at least in part by regulating AXL gene expression." (PMID 25337673, 2014). "AXL expression was induced in HPV16E6 cervical cancer cells, suggesting that blockade of AXL signaling might be an effective way to reduce the progression of cervical cancer." (PMID 34563169, 2021).
colitis (4 papers, 2017 to 2023). Inflammation of the colon. "Both mRNA and protein levels of AXL significantly increased in the inflamed colon regions of rat experimental colitis (2,4,6-trinitrobenzene sulfonic acid (TNBS) induced rat model of colitis); in addition, elevated AXL gene expression was detected in colonic lesions of IBD patients." (PMID 31752264, 2019).
colorectal adenocarcinoma (4 papers, 2021 to 2023). The most common type of colorectal carcinoma. "Evaluate the prognostic role of the biomarkers CD133, AXL and c-MYC and their association with clinicopathologic characteristics in colorectal adenocarcinomas and adenomas." (PMID 33759958, 2021). "The aim of the present study was to evaluate the prognostic role of the biomarkers CD133, AXL and c-MYC and their association with clinicopathologic characteristics in colorectal adenocarcinomas and adenomas, in a single institutional patient outcome." (PMID 33759958, 2021). "Recently, dual inhibition of TGFβ and AXL signaling pathways was proposed as a novel therapy for human colorectal adenocarcinoma with mesenchymal phenotype (CMS4), a very aggressive CRC characterized by resistance to standard chemotherapies, low survival rate and high risk of recurrence." (PMID 37469409, 2023). "Although it is not implicated as an oncogenic driver, AXL is overexpressed in several hematologic and solid malignancies, such as acute myeloid leukemia, non-small-cell lung cancer, gastric and colorectal adenocarcinoma, as well as prostate and breast cancer." (PMID 33759958, 2021).
endometriosis (4 papers, 2008 to 2025). The growth of functional endometrial tissue in anatomic sites outside the uterine body. "Therefore, the PCB126/AXL/GAS6/ESR2 axis represents a key mechanism underlying the induction of endometriosis-associated DNA methylation via DNMT3A." (PMID 41054802, 2025). "AXL activation is closely associated with endometriosis progression." (PMID 40951281, 2025). "Therefore, the PCB126/AXL/GAS6/ERβ axis represents a key mechanism underlying the induction of endometriosis-associated DNA methylation via DNMT3A." (PMID 40951281, 2025). "PCB-126 promotes endometriosis progression through coordinated activation of the AXL/ERβ/DNMT3A axis, disrupting estrogen-mediated epigenetic regulation and inducing endometriosis-associated immunoinflammatory responses." (PMID 40951281, 2025). "Collectively, these findings suggest that PCB-126 promotes endometriosis progression through coordinated activation of the AXL/ERβ/DNMT3A axis, driving estrogen-mediated epigenetic and immunoinflammatory responses." (PMID 40470214, 2025). "Our findings establish a mechanistic connection between environmental PCB126 exposure and endometriosis progression via the AXL/ESR2/DNMT3A axis." (PMID 41054802, 2025). "The ability of PCB126 to enhance ESR2 activity and stimulate endometriosis lesion growth via AXL represents a unique estrogen mimicry mechanism by which persistent organic pollutants promote estrogen-sensitive pathologies." (PMID 41054802, 2025). "Collectively, our study identifies the PCB126/AXL/GAS6/ERβ/DNMT3A axis as a key integrator of endocrine-disrupting chemical (EDC)-mediated endometriosis progression." (PMID 40951281, 2025). "Because of their expression pattern, SHC1, ACTN4, and AXL, were identified as promising endometriosis-related candidate genes, and their expression patterns were further investigated at the protein level by immunohistochemistry." (PMID 19055724, 2008). "Targeting the AXL/ESR2/DNMT3A axis may represent a novel therapeutic avenue for environmentally induced endometriosis." (PMID 41054802, 2025). "In this context, the PCB126/AXL/ERβ axis may provide a critical clue to understanding how PCB126 coordinates with ERβ to promote endometriosis progression." (PMID 40951281, 2025). "AXL, as well as the other endometriosis-related genes identified in this study, may therefore represent exciting new candidates for the detection and therapy of this disease." (PMID 19055724, 2008). "Therefore, it is possible that overexpression of AXL and GAS6 is a main cause for the activation of the PI3K-Akt pathway in endometriosis." (PMID 19055724, 2008). "For example, the use of an AXL-extracellular domain or an AXL dominant-negative receptor mutant for endometriosis treatment may be advantageous compared to conventional therapies such as GnRHa and Danazol." (PMID 19055724, 2008). "As the PI3K-Akt pathway is involved in cell survival, proliferation, and migration, its activation through GAS6/AXL may be a common central biological event during the pathogenesis of endometriosis." (PMID 19055724, 2008). "The PCB126/AXL/GAS6/ERβ/DNMT3A axis provides a critical clue for understanding how EDCs may epigenetically drive the formation of an inflammatory-immune microenvironment that promotes endometriosis progression." (PMID 40951281, 2025). "AXL may represent a promising new therapeutic target for endometriosis." (PMID 19055724, 2008). "Collectively, our study demonstrated that exposure to PCB126 indirectly upregulated Dnmt3a through the activation of the AXL/GAS6/ESR2 axis, leading to dysregulation of epigenomic regulation in the endometrium and promoting the progression of endometriosis." (PMID 41054802, 2025). "ERβ is a well-established driver of endometriosis, and PCB126 enhances ERβ activity through the AXL/GAS6 signaling axis." (PMID 40951281, 2025). "ESR2 is a well-established driver of endometriosis, and PCB126 enhances ESR2 activity through the AXL/GAS6 signaling axis." (PMID 41054802, 2025).